TIMP2 (TIMP metallopeptidase inhibitor 2)
Diseases named in the same sentence as TIMP2 in open-access papers (continued):
Sharing a sentence is not in itself a finding about the gene and the disease.
tumor (continued). "The presence of tissue inhibitors of matrix metalloproteinases 1 and 2 (TIMP-1 and TIMP-2) was also confirmed, further suggesting a complex regulatory role of ectosomes within the tumor microenvironment." (PMID 35406748, 2022). "When correlating MMP-1, MMP-2, MMP-9, TIMP-1, and TIMP-2 expression in tumor tissue in non-invasive and invasive PTC, we report significant positive correlation between TIMP-2 and MMP-2 in the non-invasive tumor group (rho = 0.378, p = 0.039)." (PMID 36551933, 2022). "TIMP2 acted as a tumor suppressor in RCC, and TIMP2 is targeted by miR-221 to regulate 786-O cell proliferation." (PMID 36578555, 2022). "The NF-κB transcription factor regulates the expression of TIMP-2 and is involved in tumor metastasis." (PMID 35770085, 2022). "The objective of our study was to examine the expression of tumor-progression-associated MMPs (MMP-1, MMP-2, and MMP-9) and tissue inhibitors of metalloproteinases (TIMP-1 and TIMP-2) in locally invasive PTC and their relation to clinicopathological features." (PMID 36551933, 2022). "They further found that MMP-10, TIMP-1, and TIMP-2 were correlated to tumor size, with TIMP-2 had the most significant impact on tumor size." (PMID 35586209, 2022). "Then we predicted and validated that TIMP2, a tumor suppressor gene, is the downstream target of miR-483-5p in MM." (PMID 35300408, 2022). "IHC was used to detect the expression of NF-κB, MMP9, MMP2, and TIMP-2, which are the four key targets for tumor migration and invasion." (PMID 35770085, 2022). "Tissue inhibitors of metalloproteinases (TIMPs) are proverbial inhibitors of metalloproteinases and composed of four structurally related members (TIMP1, TIMP2, TIMP3, and TIMP4), associated with tumor invasion and angiogenesis." (PMID 35559040, 2022). "Together, the results from an in vivo mouse study indicated that inhibiting miR-193a-5p levels in TAM exosomes can suppress ccRCC tumor progression and metastasis by suppressing VM and upregulating TIMP2 expression." (PMID 35443741, 2022). "In different TNM stages, the expression of TIMP2 had a statistical significance in size of tumor (T), nodal state (N), and metastasis (M) (P = 2.825e-9, P = 4.635e-10, and P = 1.366e-9)." (PMID 34678879, 2021). "QRT-PCR and Western blot shows that the overexpression of miR-17-5p and miR-4443 significantly down-regulated TIMP2 expression in xenografted tumor tissues." (PMID 34778021, 2021). "MMP‐2 localizes on the surface of endothelial cells and tumor cells by binding to the αvβ3 integrin or forming a ternary complex with TIMP‐2 bound to MT1‐MMP to promote the migration of these cells." (PMID 33656791, 2021). "Accumulated evidence indicates that TIMP2 plays a significant role in various tumor processes including cell growth, apoptosis, invasion, and metastasis." (PMID 34678879, 2021). "The results also suggested that TIMP2 promotes tumor progression and miR-205-5p directly regulates TIMP2, which leads to suppression of pro-MMP 2 activations and inhibition of OSCC cell invasiveness." (PMID 33806361, 2021). "MMP2 degrades ECM components of the basement membrane and facilitates tumor invasion while TIMP2 regulates MMP2 activity." (PMID 33995488, 2021). "Regarding cancer, the current findings show that the role of TIMP2 in prognosis depends on the tissue of origin of the tumor." (PMID 34781885, 2021). "Significantly, higher expression of TIMP-2 in Type-2 compared to Type-1 tumors supports the involvement of this protein in tumor progression as well as treatment outcome." (PMID 35047406, 2021). "Researchers have found that MMP-2 is over-expressed in ESCC tumor tissues, and TIMP2 is down-regulated in both tissues and serum." (PMID 34778021, 2021). "The role of MMP-2 and -9, and their tissue inhibitor, TIMP-2, have been investigated in several human neoplasms for their supposed role in cancer invasiveness." (PMID 35010907, 2021).
tumor (continued). "High expression of TIMP2 has been reported to inhibit matrix metalloproteinases to produce anti-tumor activity." (PMID 33692952, 2021). "Taken together, our research demonstrated that miR-17-5p and miR-4443 are significantly upregulated in ESCC tissues, and serve as a tumor promoter by directly targeting TIMP2." (PMID 34778021, 2021). "The miR-17-5p/4443- TIMP2 axis was shown to promote the tumor progression in vitro and in vivo experiments." (PMID 34778021, 2021). "For example TIMP-2 binds to MMP-14 on the tumor cell surface, and this binding induces cell proliferation mediated through the subsequent activation of extracellular-regulated kinases (ERK) 1/2." (PMID 34204372, 2021). "There were significant correlations between MMP-2 immunoreactivity in inflammatory cells and the presence of distant metastases, and between TIMP-2 expression in inflammatory cells and tumor size, nodal involvement and distant metastases." (PMID 34071492, 2021). "Our previous investigations have also demonstrated that serum MMP-2 and TIMP-2 concentrations decrease with tumor stage, while MMP-2 levels are significantly lower in patients with CRC in comparison to those with CA." (PMID 34071492, 2021). "TIMP-2 is a novel molecular biomarker involved in tumorigenesis and development of MM by suppressing tumor cell proliferation and metastasis." (PMID 34946293, 2021). "Studies have demonstrated that the overexpression of TIMP-2 inhibits tumor growth and angiogenesis by the upregulation of MAP kinase phosphatase 1, which dephosphorylates p38 MAPK, a molecule involved in the proliferation and migration of endothelial cells." (PMID 33419373, 2020). "In the first study, the clinicopathological role of TIMP-1 and TIMP-2 in HL was investigated by examining tumor samples obtained from 68 patients." (PMID 32751899, 2020). "In > 90% tumours TIMP-2 expression was noted in the epithelial tumour cells also expressing CA-125, while in a few others stromal expression of TIMP-2 was also noted." (PMID 33023532, 2020). "FABP5, IVL, KRT6A, KRT15, KRT16, and TIMP2 expression profiles suggested relatively significant elevated expression in tumor tissues compared with the corresponding normal tissues." (PMID 32934956, 2020). "miR-130b also acts as an oncogenic miRNA as its upregulation leads to the decreased expression of tissue inhibitor of metalloproteinase-2 (TIMP-2), which leads to increased activity in matrix metallopeptidase 2 and enhanced tumor metastasis." (PMID 32316322, 2020). "Subsequent studies have shown that an imbalance between MMP-2 and TIMP-2 concentrations in tissues can determine tumor invasion and metastasis." (PMID 32751899, 2020). "In the present study, the combined use of M-CSF, MMP-2 or TIMP-2 with the commonly accepted tumor markers resulted in an increase in SE values." (PMID 30820752, 2020). "The main goals of this thesis are to highlight the necessity for new trials to particularly focus on the involvement of selected MMPs and TIMP-2 in pediatric tumor pathogenesis and to emphasize their potential usability in assessing patient prognoses." (PMID 32751899, 2020). "The combined use of M-CSF, MMP-2 or TIMP-2 with the commonly accepted tumor markers (antigen SCC and CA 125) resulted in an increase in the sensitivity range in the total CC group." (PMID 30820752, 2020). "Previous reports have identified a number of miRNAs with the ability to target the 3′UTR of TIMP-2 mRNA in tumor cells, including miR-106a, miR-761, and miR-301a." (PMID 32481745, 2020). "TIMP-2 was detected in both invasive tumor cells and benign epithelial cells in two control cervices." (PMID 32751899, 2020). "It is now evident that TIMP-2, defined as a tissue inhibitor of MMPs, plays an important regulatory role in tumour biology through both MMP-inhibitory and MMP-independent mechanisms." (PMID 33023532, 2020). "We found that the expression levels of TIMP-2 in tumor tissues were much lower compared within the matched normal tissues." (PMID 31293204, 2019).
tumor (continued). "In the assessment of nodal staging from N0 to N3, the expression of TIMP-1 and TIMP-2 was higher in tumor tissues, compared to that in the stroma (P=0.2932, P=0.0085)." (PMID 31223594, 2019). "In tumor tissue, the balance between TIMP2, MMP2 and MMP14 is tipped in favor of MMP14 and MMP2 suggesting that the levels of MMP2 activation in tumor tissue are increased." (PMID 31882975, 2019). "Matrix metalloproteinase-2 (MMP-2) and the imbalance between MMP-2 and its tissue inhibitor (TIMP-2) play a critical role in tumor progression." (PMID 30719232, 2019). "The activation of TIMP2 in tumor cells inhibits tumor cell growth in vivo and suppresses epithelial-to-mesenchymal transition (EMT), which is associated with tumor characteristics of aggressiveness and metastatic potential." (PMID 31344121, 2019). "In this study, we provided new evidences that TIMP-2 expression in CRC tumor tissues was lower than that in matched adjacent normal tissues." (PMID 31293204, 2019). "In this study, the results of the present study suggest that miR-93 was a tumor activator in human OS via directly regulating TIMP2." (PMID 31383784, 2019). "Our data indicated that combination of the clinical risk scores (TNM stage, histologic type, and tumor diameter), TIMP-2 or MMP-9 or TIMP-2 plus MMP-9 expression predicted prognosis of CRC." (PMID 31293204, 2019). "We also demonstrated that low TIMP-2 expression in CRC tumor tissues was closely correlated with pathological classification, depth of invasion, lymph node metastasis and TNM stage." (PMID 31293204, 2019). "MMP-14 activates both MMP-2 and MMP-13, in the presence of TIMP-2, with a demonstrated effect in tumor invasion and metastasis, by promoting cell migration." (PMID 31886121, 2019). "TIMP-1 and TIMP-2 can block MMP effects in promoting tumor cell proliferation and migration and can also inhibit angiogenesis and apoptosis." (PMID 31886121, 2019). "In the author’s own research, based on the changes in the expression of tissue inhibitors of metalloproteinases in the whole studied group, a higher expression of TIMP-1 and TIMP-2 was observed in tumor tissues, compared to that in the stroma." (PMID 31223594, 2019). "Based on diagnostic sensitivity we indicated the advantage of TIMP-2 measurement over assessment of MMP-2 and classical tumor markers (CEA and CA 19-9) in the diagnosis of PC patients." (PMID 30719232, 2019). "In the present study, no statistical significance was observed regarding the expression of TIMP-1 and TIMP-2 in tumor and stroma depending on the T stage." (PMID 31223594, 2019). "Increased TIMP-2 levels in tumor tissues are correlated with a favourable prognosis in patients with NSCLC30." (PMID 31061410, 2019). "The expression of miR-93 and TIMP2 were notably correlated with tumor size, TNM stage, and distant metastasis." (PMID 31383784, 2019). "The diagnostic sensitivity of TIMP-2 (79%) was higher than MMP-2 (47%) and classical tumor markers (CA 19-9 – 71% and CEA – 37%)." (PMID 30719232, 2019). "Using a pairwise comparison of linear regression in normal and tumor tissue, we highlight multiple genes for future investigation into their relationship with TIMP2." (PMID 31882975, 2019). "In this study, we address inconsistencies in the literature regarding the role of TIMP2 in tumor progression by analyzing co-expressed genes in tumor vs. normal tissue." (PMID 31882975, 2019). "In summary, we demonstrated that TIMP-2 was an important target molecule of miR-130b in vitro and in clinical tumor tissues and serum samples from patients with NSCLC." (PMID 31061410, 2019). "The increased MMP2/TIMP2 ratio has been reported to exhibit direct correlation with advanced tumor stage, increased colorectal tumor invasion and poor prognosis." (PMID 30988064, 2019). "NB-targeted delivery of miR-34a not only decreased tumor growth, but also significantly reduced tumor vascularization by targeting TIMP2, a critical component of MDR." (PMID 31867575, 2019).
tumor (continued). "Regardless of MMPs, their specific tissue inhibitors, including TIMP-1 and TIMP-2, play an important role in tumor progression." (PMID 31223594, 2019). "In the context of tumor invasion, TIMP-2 is expected to serve as an anti-invasive/anti-metastatic agent through inhibition of MMP-2." (PMID 31088428, 2019). "A variety of scientific papers have revealed that over-expression of TIMPs, especially TIMP-1 and TIMP-2, can inhibit tumor growth, invasion and metastasis." (PMID 29356905, 2018). "In that scenario, adding TIMP-2 to the tumor microenvironment seems a logistic approach to tackle tumorigenesis." (PMID 29393911, 2018). "Consistently, the similar trend was also observed in expression levels of HG-CD147 and polylactosamines, whereas tumor metastasis-related tissue inhibitor of metalloproteinases 2 (TIMP2) expression was inhibited by c-Jun." (PMID 29719608, 2018). "There is a growing consensus which supports the notion that TIMP-2 expression levels are reduced in a variety of human tumor settings and this is correlated with enhanced tumor progression." (PMID 29393911, 2018). "For example, in the case of TIMP-3, the C-terminal domain is responsible for its unique ability to bind to the ECM and in the case of TIMP2, the C-terminal domain plays a role in its high affinity binding to the tumor cell surface." (PMID 29393911, 2018). "On the other hand, increased TIMP-2 levels in tumor tissues correlates with reduced tumor growth and enhanced sensitivity to chemotherapy." (PMID 29393911, 2018). "To verify the regulation of TIMP2 by EZH2, we performed loss- and gain-of-function experiments of EZH2 and examined TIMP2 expression, MMP2 and MMP9 expression and proteolytic activity, and tumor cell migration and invasion." (PMID 28620234, 2017). "We further investigated the role of si-TIMP2 in tumor metastasis, and western blot was performed to detect the expression of MMPs and EMT related markers." (PMID 29220395, 2017). "We further clarified that miR-93 functions as a promoter in cell proliferation and metastasis in vitro and tumor formation in vivo by direct target of TIMP2." (PMID 29220395, 2017). "TIMP2 is a member of the family of tissue inhibitors of metallopeptidases (TIMPs).The results of in vitro and in vivo studies showed that TIMP2 plays an important role in tumor progression." (PMID 27088717, 2016). "Several downstream target genes of WNT/β-catenin signaling, such as CD44, C-myc, MMP2, MMP7 and TIMP2, can affect tumor growth, proliferation, invasion and metastasis." (PMID 27835587, 2016). "We demonstrated, in the in vivo experimental model, that complexes containing AP-15 and pTIMP2 administered to mice bearing B16-F10 or L1 tumors introduced the TIMP2 gene to tumor cells with high efficiency." (PMID 27088717, 2016). "We found that PER1 knockdown not only increased MMP2 and MMP9 expression, but also decreased TIMP-2 expression, presumably leading to the observed increases in tumor cell migration and invasion." (PMID 26943040, 2016). "The pharmacological inhibition of TIMP-2 – MT1-MMP activation of pro-survival signaling can provide a novel approach to the treatment of tumor development and progression." (PMID 26331622, 2015). "TIMP2 can increase cell-cell adhesion, effectively inhibiting tumor growth, migration, and epithelial to mesenchymal transition (EMT)." (PMID 26314845, 2015). "The screening analysis by Proteome Profiler showed distinctly altered expression of sE-cadherin, E-selectin, MMP2, MMP9, TIMP1, TIMP2, Galectin and Clusterin in the serum of tumor patients compared to controls." (PMID 25967040, 2015). "LDP-TIMP2 showed better targeting activity to KYSE150 tumor xenograft than that to HT1080 and H460 tumors, by contrast, TIMP2-LDP showed little accumulation in tumor location." (PMID 26314845, 2015). "In conclusion, the data reported show a novel biological function of MT1-MMP and TIMP-2 that can have an important role in tumor biology." (PMID 26331622, 2015).
tumor (continued). "In vivo, TIMP-2 A549 xenografts exhibited reduced tumor growth by inhibiting tumor angiogenesis and inducing tumor cell apoptosis." (PMID 26556867, 2015). "For example, by inhibiting the activity of MMP-2, TIMP-2 can block tumor cell invasion thereby acting an anti-tumorigenic factor." (PMID 26361584, 2015). "Several genes showed progressive increases during tumor growth, including Mmp2, Mmp3, Mmp13 and Mmp16, whereas Timp2 and Mmp27 showed more dynamic fluctuations in expression." (PMID 25848906, 2015). "Taken together, these studies suggest that TIMP-2 increases tumor cell growth before the onset of angiogenesis during the initial period of tumor development." (PMID 26556867, 2015). "Among the four members of human TIMP family, TIMP2 has been investigated as a promising antitumor agent for its essential functions in tissue remodeling, tumor growth and angiogenesis inhibition." (PMID 26314845, 2015). "TIMP2 can bind to tumor cells in a specific and saturable mode; whereas, the identification of cell surface binding proteins for TIMP2 is complicated by the presence of MMP-14, which is remained poorly characterized." (PMID 26314845, 2015). "Here we report that in MT1-MMP expressing human tumor cells TIMP-2 also induces rapid and sustained activation of AKT in a dose- and time-dependent manner, and by a mechanism independent of the proteolytic activity of MT1-MMP." (PMID 26331622, 2015). "At the post-translational level, MT1-MMP specifically activates the latent pro-MMP-2 on the tumor cell surface through the formation of a complex with TIMP-2." (PMID 24978435, 2014). "The significant differences were also found for TIMP-2 expression in inflammatory infiltrate cell; the percentage of positive reactions decreased in patients with higher tumor size, number of lymph node involved, and metastases to distant organs." (PMID 24395652, 2014). "By contrast, TIMP-2 staining was found to correlate with age at diagnosis (P=0.026) and negatively correlate with tumor size and tumoral stage (P=0.002 and P=0.001, respectively)." (PMID 24527080, 2014). "We have found the significant associations between decreased MMP-2 expressions in inflammatory cells and distant metastases as well as between tumor invasion and reduced expression of TIMP-2 in inflammatory interstitium." (PMID 24395652, 2014). "In the sporadic form of the disease, the analysis of clinical parameters demonstrated an inverse correlation between TIMP-2 staining and tumor size (r=−0.429; P=0.02) and tumor stage (r=−0.475; P=0.006)." (PMID 24527080, 2014). "There was a significant correlation between MMP-2 immunoreactivity in inflammatory cells and the presence of distant metastases and between TIMP-2 expression in inflammatory cells and tumor size, nodal involvement, and distant metastases." (PMID 24395652, 2014). "Growth rate, apoptosis, cell cycle parameters, and expression of mRNA for proteins associated with invasiveness and tumor microenvironment (CA IX, VEGF-A, HIF-1A, MMP-9, and TIMP-2) were analyzed." (PMID 23914349, 2013). "Both MT1-MMP and TIMP-2 were found on tumor cell surfaces and membrane protrusions during transendothelial migration." (PMID 24194929, 2013). "That is, increased TIMP1 expression has been correlated with shorter overall survival of GBM patients and TIMP-2 concentrations have been reported to be greater at the tumor margin." (PMID 23349962, 2013). "Recently, a TIMP-2 fusion protein with human serum albumin (HSA/TIMP-2) was produced with high yield from the yeast Saccharomyces cerevisiae and demonstrated an inhibitory effect against tumor growth." (PMID 22545131, 2012). "Accordingly, to evaluate possible in vivo effects of HSA/TIMP-2 on apoptosis and proliferation, immunohistochemical staining data from treatment and control groups of tumor-bearing mice were compared." (PMID 22545131, 2012).